EP300 (EP300 lysine acetyltransferase)
Diseases named in the same sentence as EP300 in open-access papers (continued):
Sharing a sentence is not in itself a finding about the gene and the disease.
cancer (continued). "We compared TMB, defined as the total number of somatic mutations, between EP300-mutated and EP300-wild-type cancers." (PMID 34616736, 2021). "We found that TMB was significantly higher in EP300-mutated than in EP300-wild-type cell lines from seven of the 11 cancer types (p < 0.05)." (PMID 34616736, 2021). "In BLCA, CESC, LUAD, LIHC, and ESCA, the PGM group encompassed a higher proportion of EP300-mutated cancers than the PGW group for at least one of the nine pathways." (PMID 34616736, 2021). "We found that EP300-mutated cancers harbored a significantly higher proportion of MSI cancers than EP300-wild-type cancers in COAD and STAD [Fisher’s exact test, p < 0.05, odds ratio (OR) > 4]." (PMID 34616736, 2021). "It indicated that EP300 mutations were associated with reduced drug sensitivity of cancer cell lines to these compounds." (PMID 34616736, 2021). "We further compared a T cell-inflamed gene expression profile (T-GEP) between EP300-mutated and EP300-wild-type cancers." (PMID 34616736, 2021). "We found that the ratios (CD8+/CD4+ regulatory T cells, pro-/anti-inflammatory cytokines, and M1/M2 macrophages) were significantly higher in EP300-mutated than those in EP300-wild-type cancers in multiple cancer types (two-tailed Student’s t-test, p < 0.05)." (PMID 34616736, 2021). "Using the datasets from The Cancer Genome Atlas, we analyzed the correlations between EP300 mutations and genome instability and antitumor immune response in 11 cancer types." (PMID 34616736, 2021). "Compared to EP300-wild-type cancers, EP300-mutated cancers had significantly higher tumor mutation burden (TMB) in 10 cancer types." (PMID 34616736, 2021). "Our study demonstrates that EP300 mutations are associated with increased genome instability and antitumor immunity and thus is a predictive biomarker for the response to cancer immunotherapy." (PMID 34616736, 2021). "This study investigated the association between EP300 mutations and genome instability in 11 cancer types from The Cancer Genome Atlas1 database." (PMID 34616736, 2021). "Again, these results suggest that EP300 mutations have a significant association with genome instability in cancer." (PMID 34616736, 2021). "It indicated that EP300 mutations were associated with increased drug sensitivity of cancer cell lines to these compounds." (PMID 34616736, 2021). "Again, it suggests that EP300 mutations are associated with increased antitumor immune activity in cancer." (PMID 34616736, 2021). "Cancers with EP300/CBP loss of function (LOF; deletion and/or copy number variants [CNV] loss) showed lower ERAP1 and IFNGR1 or HLA-A expression." (PMID 33602823, 2021). "ASXL1 and EP300 are both involved in chromatin remodelling, but little is known about the functional roles of the disordered regions targeted by cancer mutations." (PMID 33806614, 2021). "Because TMB, T-GEP, and PD-L1 expression were independent positive predictors for the response to ICIs and elevated in EP300-mutated cancers, we expected that EP300 mutations would correlate with a higher rate of response to ICIs." (PMID 34616736, 2021). "This is consistent with previous results of the significant association between EP300 mutations and genome instability in cancer." (PMID 34616736, 2021). "We found that CYT scores were significantly higher in EP300-mutated than those in EP300-wild-type cancers in four cancer types, including BLCA, HNSC, STAD, and COAD (two-tailed Student’s t-test, p < 0.05)." (PMID 34616736, 2021). "This study investigated associations of EP300 mutations with genome instability and tumor immunity by pan-cancer analysis of 11 cancer types." (PMID 34616736, 2021).
cancer (continued). "Strikingly, we found that the PGM group harbored a significantly higher proportion of EP300-mutated cancers than the PGW group for all the nine pathways in SKCM, UCEC, and STAD." (PMID 34616736, 2021). "Because both high TMB and PD-L1 expression were associated with a more active response to ICIs, EP300-mutated cancers would respond better to ICIs vs. EP300-wild-type cancers." (PMID 34616736, 2021). "Consistent with its related roles in oncogenesis, EP300 is mutated at high rates in several cancers that are also associated with ARID1A loss, including basal cell (23%), bladder (15%), and uterine (15%) carcinomas." (PMID 34731603, 2021). "We found that T-GEP scores were significantly higher in EP300-mutated than in EP300-wild-type cancers in six cancer types, namely, BLCA, HNSC, UCEC, STAD, BRCA, and COAD." (PMID 34616736, 2021). "We identified several KEGG pathways highly enriched in EP300-mutated vs. EP300-wild-type pan-cancer of the 11 cancer types by GSEA." (PMID 34616736, 2021). "EP300 mutations have been found in many cancers including CRC; however, its precise role in tumorigenesis is debated and contradictory, since some studies showed a tumor suppressor function, while others showed oncogenic co-activation properties." (PMID 33096795, 2020). "At this point further assessments of the location of HPV-associated EP300 mutations and functional in vitro studies would, however, be needed to explain the high EP300 mutation frequency in HPV-related cancer." (PMID 32523042, 2020). "CREBBP and EP300 appeared to be widely mutated in multiple cancer types at a low to modest frequency (0.2–13.5% and 0.2–14.8%, respectively) and PBRM1 was highly mutated in KIRC (40.1%)." (PMID 30760718, 2019). "For example, CREBBP and EP300 were widely mutated across multiple cancer types at relatively low frequencies; most of these mutations were heterozygous missense mutations." (PMID 30760718, 2019). "Another critical gene included in this module is EP300, it encodes the transcriptional cofactor p300, which is highly expressed in diverse human cancers." (PMID 29179495, 2017). "EP300 is also a known driver gene in other types of cancer, and germline variants in EP300 have been shown to confer inherited risk of pediatric ALL in a Hispanic population." (PMID 27590521, 2016). "Proteins called CBP and EP300 are two examples of regulatory proteins, and have been implicated in promoting various cancers in humans." (PMID 26731516, 2016). "Strikingly, some reports have linked the expression of wild-type EP300 in colorectal and prostate cancer with the degree of intravascular dissemination of cancer cells (probably affected by ongoing EMT) and poor prognosis." (PMID 25883651, 2015). "Importantly, we find that the loss of EP300 results in decreased expression of BRCA2 protein leading to sensitivity to treatments that are cytotoxic to BRCA-deficient cancers." (PMID 41354653, 2025). "EP300 mutated cancers closely resemble BRCA-deficient tumors." (PMID 41354653, 2025). "Overall, we demonstrate that EP300-mutated cells recapitulate features of BRCA-deficient cancers." (PMID 41354653, 2025). "To do so, we integrated expression, mutation and dependency data from the Cancer Cell Line Encyclopedia (CCLE) and the Cancer Dependency Map (DepMap) to investigate whether mutational status of EP300 or CBP predicted differential response to CCS1477 or A485." (PMID 38664416, 2024). "Therefore, in this study, we focused on the paralog pair CREBBP and EP300 as a synthetic lethal target for SMARCB1-deficient cancers." (PMID 38839769, 2024). "Genes encoding KDM6A, KMT2D and EP300 are highly mutated in human cancers." (PMID 37410700, 2023). "Notably, among the six BCa-associated EP300 missense mutants, EP300-R1627W was the only one that was recurrent in different cancers." (PMID 36647005, 2023). "Elevated cell cycle activity in EP300-mutated cancers indicates that this subtype could have a favorable response to cell cycle inhibitors." (PMID 34616736, 2021).
cancer (continued). "Also, EP300-mutated cancers showed significantly higher programmed death-ligand 1 (PD-L1) expression levels than EP300-wild-type cancers." (PMID 34616736, 2021). "In cancer, EP300 has been previously reported to target both mutations and structural alterations, which could be an important contributor to malignant transformation." (PMID 33922652, 2021). "Furthermore, EP300 was co-mutated with at least one of the seven DNA mismatch repair genes (p = 2.55 × 10–8, OR = 3.6) in the cancer cell lines." (PMID 34616736, 2021). "E1A binding protein p300 (EP300) is mutated in diverse cancers." (PMID 34616736, 2021). "Furthermore, because of increased TMB to create more neoantigens due to DDR deficiency, EP300-mutated cancers displayed stronger antitumor immune activity." (PMID 34616736, 2021). "Likewise, we found that EP300 mutations were associated with increased drug sensitivity of cancer cell lines to many compounds in individual cancer types." (PMID 34616736, 2021). "Overall, these results suggest that EP300 mutations may enhance the sensitivity of cancers to many antitumor drugs." (PMID 34616736, 2021). "EP300 mutations, largely missense point mutations, are found across a wide variety of cancer types." (PMID 34452526, 2021). "Moreover, CRC cells have particularly high mutation rates in CREBBP and EP300 genes when compared to other cancer cell types." (PMID 34258881, 2021). "Interestingly, in 10 of the 11 cancer types (except ESCA), EP300-mutated cancers had significantly higher TMB than that in EP300-wild-type cancers (one-tailed Mann–Whitney U test, p < 0.05)." (PMID 34616736, 2021). "In addition, in BRCA and COAD, the PGM group included a significantly higher proportion of EP300-mutated cancers than the PGW group for seven of the nine pathways." (PMID 34616736, 2021). "Loss of EP300 by inactivating mutations may contribute to tumorigenesis in human cancers, including gastric cancers." (PMID 30514953, 2018). "Thus, gene mutations influencing the structure of EP300 are found in several types of cancer, including BCL." (PMID 28725161, 2017). "Besides the well-known MPM-associated genes, CDKN2A, NF2 and BAP1, other interesting cancer-associated genes were listed as frequently involved in a copy number loss (e.g. EP300, SETD2 and PBRM1)." (PMID 29371938, 2017). "Interestingly, chromatin regulators such as the histone methyltransferase MLL2, the chromatin remodeling gene ARID1A, the histone demethylase KDM6A and the histone acetyltransferase EP300 were frequently mutated in this cancer type." (PMID 25473433, 2014). "In addition, the activity of CREBBP/EP300 has been implicated in several types of human cancers." (PMID 40338073, 2025). "Through its HAT activity, EP300 provides epigenetic tags for transcriptional activation and regulates important cellular processes, including cell proliferation, differentiation, and apoptosis, and its dysregulation has been associated with oncogenesis and cancer progression." (PMID 37954147, 2023). "Finally, we identified putative pathogenic alterations in multiple cancer genes, including genes involved in epigenome editing and 3D genome organization, such as EP300, CTCF, and STAG2, which we validated by targeted sequencing of an independent cohort of 115 BM samples." (PMID 36561283, 2022). "The expressional loss of EP300 might be one of the meaningful characteristics for MSI-H cancers." (PMID 35242279, 2022). "Consequently, the mutation of EP300 has correlations with cancer development and prognosis." (PMID 34616736, 2021). "Furthermore, compared to EP300-wild-type cancers, EP300-mutated cancers had significantly higher immune cytolytic activity scores and ratios of immune-stimulatory over immune-inhibitory signatures in diverse cancers." (PMID 34616736, 2021). "In addition, the cell cycle pathway was also highly enriched in EP300-mutated cancers." (PMID 34616736, 2021).
cancer (continued). "Moreover, EP300 mutations were associated with increased PD-L1 expression in diverse cancers." (PMID 34616736, 2021). "We also show that mutations in two of these genes, MLL and EP300, correlate with broad expression changes across cancer cell lines, thus presenting at least one mechanism through which these mutations could contribute to tumorigenesis in cells of the corresponding tissues." (PMID 24063517, 2013). "Several of these genes, including KEAP156,57,58 and EP300,59,60,61 are well-known cancer drivers or regulators of NFE2L2 activity, and targeting this axis has recently been implicated in re-sensitization strategies." (PMID 41492468, 2026). "In cancer, Nrf2 can recruit the E1A-binding protein p300 (EP300), thereby enhancing the H3K27 acetylation modification of SOD2, which counters oxidative stress and inhibits ferroptosis (Upper-middle)." (PMID 41513612, 2026). "Loss-of-function mutations in EP300/KAT3B and CBP/KAT3A have been implicated in the pathogenesis of cancer." (PMID 41354653, 2025). "In the pan-cancer cohort, the presence of mutations in at least one of these genes was associated with a two-fold improvement in survival compared with WT CREBBP/EP300 tumors." (PMID 41301688, 2025). "A similar observation was previously reported in a pan-cancer analysis highlighting EP300 as a marker of genomic instability." (PMID 41301688, 2025). "This likely reflects the modest sample size, cell-type heterogeneity in whole lung tissue, and elevated EP300 expression in cancer-adjacent control samples." (PMID 41402732, 2025). "Our results match patterns observed in large-scale drug-sensitivity studies, which have found many cancer cell lines to be insensitive to CREBBP/EP300 inhibitors." (PMID 40239999, 2025). "In the pan-cancer cohort, patients with mutations in the target genes exhibited a median overall survival of 34 months, twice that observed in the WT CREBBP/EP300 group (17 months; log-rank p-value = 2.4 × 10−3)." (PMID 41301688, 2025). "Further we also identify key master cancer regulators like SMAD4, EP300, KAT6A and TAF1 which are associated with multiple cancers and are related to critical oncogenic processes." (PMID 41404623, 2025). "The downregulation of TGF-β—driven by reduced H3K14ac via EP300/CBP inhibition —disrupts intratumoral immunosuppression earlier in cancer pathogenesis." (PMID 41283357, 2025). "EP300 (E1A binding protein p300) played a significant role in serial diseases such as cancer, neurodegenerative disease." (PMID 38835125, 2024). "EP300 and its homologue CREBBP encode highly related acetyltransferases that act as transcriptional coactivators in multiple signaling pathways, suggesting the potential involvement of EP300/CREBBP in cancers." (PMID 38693103, 2024). "EP300 knockdown, on the other hand, reduces cancer stem cell phenotype, EMT, tumour growth and metastasis in these cancers, further supporting its oncogenic role and potential involvement in stem-like phenotype." (PMID 39419971, 2024). "Consistent with links to cancer, trials occurred or are under way that target EP300/CBP (NCT05488548, NCT03568656, NCT04068597, and NCT04575766)." (PMID 38914477, 2024). "This underscores the broader potential of EP300/CREBBP inhibition in steroid receptor-driven cancers, with FOXA1 signaling occupying a central role in these effects." (PMID 38564048, 2024). "EP300/CBP are critical gene-regulatory targets in cancer, with existing high potency inhibitors of either the catalytic HAT domain or protein-binding bromodomain (BRD)." (PMID 38664416, 2024). "Along with EP300/CBP, other KATs are implicated in cancer development and progression as well as other diseases." (PMID 38914477, 2024).
cancer (continued). "Post-treatment cold tumors also acquired more cancer-specific mutations (i.e., BRCA2, TPR, OMD, RANBP2, EP300)." (PMID 38714665, 2024). "EP300 is also an attractive therapeutic target in cancer due to its roles in promoting growth and transformation." (PMID 39681067, 2024). "EP300 is one of the most studied HATs participating in the development of many diseases, including cancer and some cardiovascular conditions." (PMID 36910531, 2023). "This methylation signature is known to be a mark of tissue-specific EP300 activity, and involved in cell growth and division in cancers." (PMID 37601663, 2023). "This evidence highlights the crucial role played by SMYD3, TRRAP, and EP300 in cancer-related epigenetic reprogramming processes." (PMID 37954147, 2023). "For instance, EP300 is largely acknowledged in cancer therapy for its advanced roles in SE organization and oncogenes transcription regulation." (PMID 36318256, 2023). "The human acetyltransferase paralogs EP300 and CREBBP are master regulators of lysine acetylation whose activity has been implicated in various cancers." (PMID 37292747, 2023). "Four of the five NF2 mutations present were approximately clonal (cancer cell fraction >0.75), while two out of three FAT1, PTPRT, and EP300 mutations each were approximately clonal." (PMID 35288096, 2022). "Our current study provides evidence on the role of EP300 in cancer cell response to cisplatin and the possible involvement of this enzyme in gaining a multidrug-resistant phenotype of A549 and MDA-MB-231 cell lines." (PMID 35205642, 2022). "EP300 mutation and loss of GATA6 function bypassed the antidifferentiation activity of Wnt signaling, rendering these cancer cells resistant to Wnt inhibition." (PMID 35536676, 2022). "CBP and its highly homologous paralog EP300 (collectively CBP/EP300) belong to the histone acetyltransferase family, which are central players in chromatin remodeling and gene activation in cancer." (PMID 35244291, 2022). "The high mutation rates of epigenetic regulators such as H3F3A, KDM5A, and EP300 suggest a unique etiologic aspect of AYA cancers that remains poorly understood." (PMID 36433963, 2022). "There are numerous reports showing the involvement of mutations in genes encoding HATs (EP300, P300, CBP, MOZ, etc.)in many cancers." (PMID 35965507, 2022). "Again, these data suggest an essential role of EP300 in regulating various cellular and molecular processes in cancer." (PMID 34616736, 2021). "We also found that EP300 and CBP LOF mutations and CNVs are rather common in certain types of cancer, and that their presence correlates with reduced MHC-I AgPPM expression." (PMID 33602823, 2021). "The enrichment of EP300 or SMYD2 in the promoter region of LINC01605 were much higher in cancer tissues than that in ADJ tissues." (PMID 34544413, 2021). "We found that EP300-mutated cancers showed more neoantigens than EP300-wild-type cancers in eight cancer types (p < 0.05)." (PMID 34616736, 2021).